SEMA3E (semaphorin 3E)
Description:
Plays an important role in signaling via the cell surface receptor PLXND1. Mediates reorganization of the actin cytoskeleton, leading to the retraction of cell projections. Promotes focal adhesion disassembly and inhibits adhesion of endothelial cells to the extracellular matrix. Regulates angiogenesis, both during embryogenesis and after birth. Can down-regulate sprouting angiogenesis. Required for normal vascular patterning during embryogenesis. Plays an important role in ensuring the specificity of synapse formation (By similarity).
Synonyms: KIAA0331; SEMAH; M-SemaK; coll-5; M-SEMAH
Tractability: Antibody: its Gene Ontology location is reachable by antibodies, with high confidence; UniProt places it where antibodies can reach, with medium confidence; UniProt predicts a signal peptide or a membrane-spanning region. PROTAC: ubiquitination databases record sites on it.
Gene: Protein-coding gene on chromosome 7 (83,363,238 to 83,649,139, reverse strand). Ensembl gene ENSG00000170381.
Subcellular location: Secreted
Subcellular location (Human Protein Atlas): Vesicles; Nucleoplasm; Predicted to be secreted
Pathways (Reactome):
Developmental Biology: Other semaphorin interactions
Gene Ontology:
Molecular function: protein binding; receptor ligand activity; semaphorin receptor binding; chemorepellent activity; neuropilin binding
Biological process: gonadotrophin-releasing hormone neuronal migration to the hypothalamus; negative regulation of neuron apoptotic process; positive regulation of phosphatidylinositol 3-kinase/protein kinase B signal transduction; semaphorin-plexin signaling pathway; axon guidance; branching involved in blood vessel morphogenesis; negative chemotaxis; negative regulation of angiogenesis; negative regulation of cell-matrix adhesion; neural crest cell migration; positive regulation of cell migration; sprouting angiogenesis; synapse organization; forebrain development; regulation of cell shape
Cellular component: extracellular region; plasma membrane
Genetic constraint (gnomAD): Loss-of-function variants: 45 observed, 86.38 expected, observed/expected ratio (o/e) 0.52, 90% interval 0.41 to 0.67. The upper end of that interval is the gene's LOEUF score, 0.67, which puts it in group 2 of 6, group 1 being the genes least tolerant of losing a copy. Missense variants: 849 observed, 943.15 expected, observed/expected ratio (o/e) 0.9, 90% interval 0.85 to 0.95. Synonymous variants: 347 observed, 331.27 expected, observed/expected ratio (o/e) 1.05, 90% interval 0.96 to 1.14.
Homologues: Orthologues: chimpanzee SEMA3E (99% identical), macaque SEMA3E (99% identical), pig SEMA3E (93% identical), mouse Sema3e (90% identical), dog SEMA3E (90% identical), rat Sema3e (89% identical), tropical clawed frog sema3e (74% identical), guinea pig SEMA3E (71% identical), zebrafish sema3e (58% identical). Paralogues in human: SEMA3G (51% identical), SEMA3A (47% identical), SEMA3D (44% identical), SEMA3B (44% identical), SEMA3F (43% identical), SEMA3C (42% identical), SEMA4D (28% identical), SEMA4C (28% identical), SEMA4G (27% identical), SEMA4B (27% identical), SEMA5B (27% identical), SEMA6D (26% identical), and 7 more.
Diseases named in the same sentence as SEMA3E in open-access papers:
SEMA3E is named in the same sentence as 102 diseases in open-access papers, as found by Europe PMC text mining. Sharing a sentence is not in itself a finding about the gene and the disease. The quoted sentences say what the papers report.
CHARGE syndrome (13 papers, 2012 to 2025). CHARGE syndrome is a multiple congenital anomaly syndrome characterized by the variable combination of multiple anomalies, mainly Coloboma; Choanal atresia/stenosis; Cranial nerve dysfunction; Characteristic ear anomalies (known as the major 4 C's). "While there is an established association between SEMA3E and CHARGE syndrome, more recent GWAS suggest that variants in the SEMA3E locus are associated with neurological and psychiatric phenotypes." (PMID 39787209, 2025). "The loss-of-function mutations in SEMA3E are formally associated with CHARGE syndrome, a complex multisystem genetic disease characterized by ocular coloboma, congenital heart defects, retardation of growth, genital hypoplasia, and facial asymmetry." (PMID 36437957, 2022). "First, SEMA3E mutations have been reported in a CHARGE syndrome patient presenting bilateral choanal atresia, cranial nerve dysfunction, genital hypoplasia, developmental delay, and growth retardation." (PMID 33869187, 2021). "Another member of the class 3 semaphorins, SEMA3E, has recently been implicated in the NC defects that are found in CHARGE syndrome." (PMID 33869187, 2021). "Consistent with this, mutations in SEMA3E have been identified in patients with CHARGE syndrome and knockout of sema3e in zebrafish phenocopies chd7 knockout phenotype." (PMID 33182738, 2020). "One overlapped three exons of the SEMA3D gene coding for semaphorin 3D and the other overlapped the first intron of the SEMA3E gene, previously associated with CHARGE syndrome." (PMID 22912587, 2012). "Although most commonly due to mutations involving the chromodomain helicase DNA-binding protein-7, CHARGE syndrome can be caused by mutations in the SEMA3E gene." (PMID 22912587, 2012). "Recently, a missense mutation in SEMA3E was identified in a patient suffering from CHARGE syndrome." (PMID 33837646, 2021). "In the zebrafish chd7 mutant that models CHARGE syndrome, sema3e knockdown resulted in severe craniofacial malformations, including small eyes, defective cartilage, and an abnormal number of otoliths." (PMID 33869187, 2021). "Thus, Carl and colleagues suggested that impaired SEMA3E‐PLXND1 signalling was an aetiological factor in CHARGE syndrome." (PMID 33837646, 2021). "In addition, SEMA3E mutations have also been reported in a single CHARGE syndrome patient, supporting the possible genetic interactions between semaphorins and CHD7, the main gene mutated in CHARGE syndrome." (PMID 34502334, 2021). "A similar scenario with a different outcome involves subject Clin6 who was referred for EpiSign analysis as a result of negative molecular sequencing (CHD7 and SEMA3E), negative microarray, and negative exome analysis with the phenotype strongly suggestive of CHARGE syndrome." (PMID 33547396, 2021). "However, there is little additional evidence that SEMA3E has a major role: only one de novo missense mutation in SEMA3E was found in a cohort of 24 patients with CHARGE syndrome, and Sema3e mutant mice do not phenocopy any of the cardinal features of CHARGE syndrome." (PMID 26411921, 2015). "While previous findings related to the SEMA3E gene have not been specific to ASD, chromosome 7q21.11 microdeletions involving this gene are described in patients with CHARGE syndrome (MIM# 214800) for whom the behavioral phenotype of Autism is frequently reported." (PMID 36153334, 2022).
breast cancer (10 papers, 2011 to 2023). A primary or metastatic malignant neoplasm involving the breast. "In vitro, Tgif1-deficient osteoblasts reduced breast cancer cell migration in a Sema3E-dependent manner." (PMID 32272947, 2020). "The expression of Sema3E is positively associated with metastatic potential in breast cancer, ovarian cancer, melanoma cancer and colon cancer." (PMID 26036259, 2015). "For instance, although expressions of all SEMA3 genes are associated with a better prognosis based on the survival analyses in breast cancer, SEMA3E and SEMA3F was found to be associated with more aggressive HER2 and basal like molecular subtypes, indicating a tumor promoter role in those subtypes." (PMID 32241267, 2020). "Semaphorin 3E (Sema3E), which is abundantly secreted by Tgif1−/− osteoblasts, dose-dependently reduced breast cancer cell migration while silencing of Sema3E expression in Tgif1−/− osteoblasts partially restored the impaired migration." (PMID 32272947, 2020). "Consistently, our findings suggest that osteoblast-derived Sema3E suppresses breast cancer cell migration, providing a novel paracrine function for Sema3E." (PMID 32272947, 2020). "Together, these results suggest that Tgif1 in osteoblasts supports breast cancer cell migration by suppressing Sema3E expression." (PMID 32272947, 2020). "In support of our concept, recombinant Sema3E dose-dependently impaired breast cancer cell migration." (PMID 32272947, 2020). "Analysis of human breast cancer showed elevated Sema3E expression in metastatic breast cancer as well." (PMID 30598022, 2018). "Sema3E knock-down in breast cancer cell lines triggered their apoptotic death which was rescued by rSema3E additions to cell cultures." (PMID 30598022, 2018). "In contrast with SEMA5A, other semaphorins like Semaphorin 7A in breast cancer cells and Semaphorin 3E through PlexinD1 axis in ovarian cancer cells are known to mediate EMT." (PMID 30577767, 2018). "To test Sema3E antibody for use in immunohistochemical analysis, we evaluated Sema3E expression in prostate cancer, mammary cancer, ovarian cancer and uterine cancer." (PMID 26036259, 2015). "Sema3A, sema3D, sema3E and sema3G overexpression in breast cancer cells significantly inhibits the development of tumor in xenograft models and decreases the number of intra-tumor blood vessels, suggesting an anti-angiogenic role of these molecules." (PMID 24212788, 2011). "Importantly, conditioned medium collected from Tgif1−/− osteoblasts transfected with siRNA against Sema3E partially but significantly restored breast cancer cell migration to the level of medium conditioned by Tgif1+/+ osteoblasts." (PMID 32272947, 2020). "Since Sema3E has been shown to inhibit the migration of various cell types, we hypothesized that Sema3E could also restrict the motility of breast cancer cells." (PMID 32272947, 2020). "To test this hypothesis, we allowed breast cancer cells to migrate towards increasing concentrations of Sema3E (100 ng/ml and 500 ng/ml)." (PMID 32272947, 2020). "Indeed, Semaphorin 3E (Sema3E) is described as an enhancer of tumor growth and metastasis in vitro and in vivo in xenograft experiments using breast cancer cells." (PMID 24212788, 2011). "Focusing on the PlexinD1 receptor in breast cancer, PlexinD1 was shown to drive a significant increase in caspase-dependent cell death that was inhibited by recombinant SEMA3E, suggesting that SEMA3E’s potential oncogenic role may be in part through halting apoptosis induced by unliganded PlexinD1." (PMID 37685898, 2023). "Absence of Tgif1 in osteoblasts resulted in suppressed breast cancer cell migration and bone metastases, which is mediated through increased Semaphorin 3E (Sema3E) expression." (PMID 35994202, 2022). "In the circulation, increased sNRP1 levels were associated with poor prognosis in patients with melanoma and early breast cancer, while to our knowledge, no data about serum Sema3E in tumors have been reported so far." (PMID 35888144, 2022).
breast cancer (continued). "We propose that the lack of Tgif1 in osteoblasts attenuates breast cancer cell migration and metastasis formation, presumably through suppression of Sema3E expression." (PMID 32272947, 2020). "We propose that the lack of Tgif1 in osteoblasts increases Sema3E expression and attenuates breast cancer cell migration as well as metastases formation." (PMID 32272947, 2020).
asthma (8 papers, 2017 to 2025). "In this study, Sema3E deficiency significantly influences airway responsiveness and lung function in different asthma models." (PMID 40512736, 2025). "In summary, Sema3E deficiency in type-2 low asthma mediates more severe airway inflammation and exaggerated type-1 cytokines profile, while in the type-2 high it induced enhanced type-2 cytokines and milder airway inflammation." (PMID 40512736, 2025). "The increased number of DCs and CD4 + T cells in the lungs of Sema3E-deficient mice in the type-2 low asthma model, compared to WT mice, highlights the broader impact of this axis on immune regulation beyond granulocytes." (PMID 40512736, 2025). "The work by Movassagh and associates defined the effect of Sema3E deficiency in experimental mouse model of asthma." (PMID 30134791, 2018). "In order to completely understand the mechanism underlying therapeutic effect of Sema3E on HDM chronic model of asthma, a detailed investigation of is PlexinD1 expression and function is required." (PMID 29228740, 2017). "In the type 2-low asthma model, Sema3E-deficient mice exhibited increased tissue resistance and elastance, accompanied by elevated levels of neutrophils, dendritic cells, CD4 + T cells, and pro-inflammatory cytokines such as IL-17, TNF, IL-1β, CXCL-8, and MCP-1/CCL2." (PMID 40512736, 2025). "Therefore, reduction of AHR via balancing type 2-biased allergic inflammation by Sema3E could be an underlying mechanism of Sema3E action in asthma." (PMID 29228740, 2017). "Accordingly, we investigated the levels of pro-/anti-inflammatory cytokines in Sema3E KO and WT counterparts in both type-2 low and type-2 high models of asthma." (PMID 40512736, 2025). "Our investigation has unveiled a clear divergence in the pattern of Sema3E form expression between pulmonary fibrosis and asthma." (PMID 40112179, 2025). "In this study, we investigated Sema3E’s role in a type-2 low asthma model and compared the results with a type-2 high model." (PMID 40512736, 2025). "Our findings reveal the dichotomous and selective homeostatic roles of Sema3E in asthma models with distinct severities, immune niches, and inflammatory responses." (PMID 40512736, 2025). "Both tissue resistance (G) and tissue elastance (H) showed a statistically significant increase in the Sema3E KO type-2 low asthma model that peaked at the 25 mg/ml methacholine dose (p < 0.05) compared with the WT counterpart." (PMID 40512736, 2025). "In this study, the deletion of Sema3E significantly altered inflammatory cell recruitment and cytokine production across different asthma models." (PMID 40512736, 2025). "Overall, Sema3E ablation significantly increases goblet cell hyperplasia and mucus production in the type-2 high asthma model." (PMID 40512736, 2025). "Sema3E ablation significantly increased goblet cell hyperplasia compared to WT mice (p < 0.01) in the type-2 high asthma model." (PMID 40512736, 2025). "Overall, our study reveals that the Sema3E regulatory network is highly context-dependent, underscoring its pivotal role in orchestrating immune and structural responses across distinct asthma phenotypes." (PMID 40512736, 2025). "The Sema3E regulatory network varies depending on the immunization regimen, affecting distinct parameters in type-2 low and type-2 high asthma models." (PMID 40512736, 2025). "In comparison to WT mice, Sema3E KO mice exhibited an enhanced tissue resistance and tissue elastance in the type 2-low asthma model." (PMID 40512736, 2025). "Initially, we assessed the impact of Sema3E deficiency on baseline and allergen-induced AHR in type-2 low and compared to type-2 high models of asthma through the evaluation of lung function parameters using the methacholine test." (PMID 40512736, 2025). "Studies indicate that Sema3E-deficient mice exhibit increased neutrophil influx into the lungs in both acute and chronic HDM models of asthma." (PMID 40512736, 2025).
asthma (continued). "Sema3E KO mice in the type 2-low asthma model exhibited an increasing trend to sensitivity to methacholine." (PMID 40512736, 2025). "We assessed the effect of Sema3E deletion on immune cell composition or recruitment into the lungs using flow cytometry in both type-2 low and type-2 high models of asthma." (PMID 40512736, 2025). "Specifically, investigations have revealed significant downregulation of Sema3E expression in the bronchoalveolar lavage fluid and lung tissues of asthma patients compared to normal subjects." (PMID 40112179, 2025). "We investigated goblet cell hyperplasia and mucus production using Periodic acid-Schiff (PAS) staining in Sema3E KO and WT counterparts in both type-2 low and type-2 high models of asthma." (PMID 40512736, 2025). "We measured the levels of total and HDM specific antibodies and the number of B cells producing antibodies in Sema3E KO and WT counterparts in both type-2 low and type-2 high models of asthma." (PMID 40512736, 2025). "Our lab demonstrates that Sema3E plays a modulatory role in allergic HDM model of asthma, and the Sema3E-plexinD1 signaling to be critical for maintaining homeostatic conditions within the airways." (PMID 40512736, 2025). "This suggests that Sema3E plays a regulatory role in mucus production, highlighting its selective action across different tissue niches and asthma phenotypes." (PMID 40512736, 2025). "Overall, these findings demonstrate that the global ablation of Sema3E led to more exaggerated bronchoconstriction and poor lung function in type-2 low compared to type-2 high asthma model." (PMID 40512736, 2025). "Other parameters of AHR, such as tissue resistance (G) and tissue elastance (H) were investigated to better understand the lung function in Sema3E KO and WT mice in both type-2 low and type-2 high asthma models." (PMID 40512736, 2025). "Previous research from our group has demonstrated the pivotal roles of Sema3E and its receptor PlexinD1 in regulating airway inflammation, remodeling, and hyperresponsiveness in asthma." (PMID 39213301, 2024). "Analysis of airway resistance revealed pronounced AHR in OVA-induced asthma mice while Sema3E-treated mice exhibited significantly less AHR." (PMID 38111650, 2023). "OVA-induced asthma mouse model showed an increase of collagen deposition and mucus production compared with NS and AS + Sema3E groups." (PMID 38111650, 2023). "Third, this study explored preliminary the role of Sema3E in asthma AHR and airway inflammation, and further research is needed on its specific mechanisms." (PMID 38111650, 2023). "Sema3E-treated asthma mice displayed ameliorated airway hyperresponsiveness, mucus production, and collagen deposition." (PMID 38111650, 2023). "This study was the first to explore the difference in the expression of Sema3E in vagal ganglia and lung tissue of asthma and EB mice." (PMID 38111650, 2023). "Intranasal treatment with exogenous Sema3E alleviated chronic features of allergic asthma and restored airway homeostasis via regulation of mediators involved in asthma pathology." (PMID 29228740, 2017). "Data from this study unveil a key regulatory role of Sema3E in chronic course of asthma via orchestration of impaired inflammatory and remodeling responses." (PMID 29228740, 2017). "However, we did not observe any significant changes in severity of inflammation in Sema3E KO mice compared to their WT counterparts in both type-2 low and type-2 high models of asthma." (PMID 40512736, 2025). "Additionally, Rrs is elevated two-fold in both Sema3E KO and WT type-2 high mice relative to naïve controls, indicating that type-2 low asthma presents a more severe phenotype in terms of physiology and lung function than the type-2 high model (p < 0.05)." (PMID 40512736, 2025). "While the exact mechanisms by which Sema3E regulates granulocytes remain unclear, it is evident that this axis influences neutrophil and eosinophil migration and inflammatory responses in asthma." (PMID 40512736, 2025).